SP1 (Sp1 transcription factor)
Diseases named in the same sentence as SP1 in open-access papers (continued):
Sharing a sentence is not in itself a finding about the gene and the disease.
skin cancer (3 papers, 2009 to 2021). "This study concludes that PCC-1 treatment in skin cancer cells leads to apoptosis through inhibition of Sp1." (PMID 34531430, 2021). "Sp1 mRNA and DNA-binding activities are shown to increase in epithelial tumors, suggesting that increased Sp1 activity contributes to skin tumor progression." (PMID 24324617, 2013). "Therefore, to investigate the anticancer effect of PCC-1 on the transcription factor Sp1 in human skin cancer cell lines SK-MEL-28 and G361, we evaluated the anticancer activity according to the treatment concentration." (PMID 34531430, 2021). "In addition, in order to check which pathway (intrinsic or extrinsic) PCC-1 regulates Sp1 in skin cancer cell lines, translation was inhibited through CHX and then PCC-1 was treated." (PMID 34531430, 2021).
small cell lung carcinoma (3 papers, 2014 to 2024). Small cell lung cancer (SCLC) is a highly aggressive malignant neoplasm, accounting for 10-15% of lung cancer cases, characterized byrapid growth, and early metastasis. "In small cell lung cancer cells, Sp1 could function as a positive regulator for SLC31A1 expression and the influence of Sp1 to intracellular Cu concentration was reliant on its zinc finger motif." (PMID 39659361, 2024).
thyroid tumor (3 papers, 2013 to 2021). A benign or malignant neoplasm affecting the thyroid gland. "Also, compared with normal tissues, the expression of SP1 was significantly reduced in primary thyroid tumor samples." (PMID 33162555, 2021).
tongue squamous cell carcinoma (3 papers, 2015 to 2019). A squamous cell carcinoma that arises from the tongue. "The inhibition of Sp1 by miR-29b resulted in the upregulation of PTEN in tongue squamous cell carcinoma." (PMID 26063204, 2015). "Moreover, Sp1 could bind to the promoter of PTEN, which was consistent with a previous study of tongue squamous cell carcinoma." (PMID 28422727, 2017).
vitiligo (3 papers, 2015 to 2024). Generalized well circumscribed patches of leukoderma that are generally distributed over symmetric body locations and is due to autoimmune destruction of melanocytes. "Furthermore, GABARAPL2, RELA, TBC1D17, and USP8, except of SP1, are implicated in cellular responses to stress and external stimuli; External stimuli, such as stress and oxidative stress, are vital factors in the etiology of vitiligo." (PMID 37287971, 2023). "Then, five mitophagy hub genes (GABARAPL2, SP1, USP8, RELA, and TBC1D17) were identified using two machine learning algorithms, and these genes showed high diagnostic specificity for vitiligo." (PMID 37287971, 2023). "We also found that declined SP1 mRNA level in vitiligo patients and a strongly positive correlation between SP1 and AHR expressions." (PMID 26370050, 2015). "Consistent with our results, SP1 was downregulated in vitiligo." (PMID 37287971, 2023). "In summary, we provide evidence that AHR –129C > T variant could lead to allele-specific binding of SP1 to AHR promoter and further modify its transcription and downstream effectors in vitiligo." (PMID 26370050, 2015). "The AUC values of hub genes were high in the combined dataset (GABARAPL2, AUC=0.988; USP8, AUC=0.94; RELA, AUC=0.927; SP1, AUC=0.894; and TBC1D17, AUC=0.927), implying that the five hub genes have high specificity for vitiligo and could be used as vitiligo diagnostic biomarkers." (PMID 37287971, 2023). "Consistent with the bioinformatic analysis results, GABARAPL2 and USP8 mRNA levels were raised in vitiligo lesions, whereas the mRNA levels of RELA, TBC1D17, and SP1 were decreased." (PMID 37287971, 2023). "The results showed elevated GABARAPL2 and USP8 and decreased RELA, SP1, and TBC1D17 in vitiligo compared to healthy controls, which were consistent with bioinformatic analysis results." (PMID 37287971, 2023). "Through LASSO regression analysis and the random forest algorithm, we screened five mitophagy-related hub DEGs (GABARAPL2, USP8, RELA, SP1, and TBC1D17) in vitiligo." (PMID 37287971, 2023). "We subsequently found reduced peripheral AHR and SP1 transcript expressions in vitiligo and a negative correlation of AHR level with disease duration." (PMID 26370050, 2015).
AIDS (2 papers, 2020 to 2021). A syndrome resulting from the acquired deficiency of cellular immunity caused by the human immunodeficiency virus (HIV). "SP1 is critically important as one of the major targets for therapeutic drugs against HIV-1 and AIDS." (PMID 33863979, 2021). "Preliminary evidence suggests that sequestration of Sp1 by IFI16 also promotes HIV-1 latency, which represents the major obstacle against the cure of HIV/AIDS." (PMID 33353088, 2020). "Sp1 is also important for transcription of HIV-1, the etiologic agent of AIDS." (PMID 33353088, 2020).
amyloid (2 papers, 2017 to 2019). "We confirmed that ROCK1‐associated transcription factors, SP1 and SP6, were associated with amyloid production and up‐regulated in AD mouse model and those results were consistent with previous reports." (PMID 31287605, 2019). "In a recent study, pharmacological inhibition of SP1 in a mouse model of AD resulted in accelerated amyloid pathology and impaired cognitive function." (PMID 28367114, 2017).
autoimmune conditions (2 papers, 2021 to 2025). "New evidence of immune activity, such as elevated cytokines (BAFF, IFN-α), and novel autoantibodies (SP-1, CA-VI), further supports the concept of subclinical autoimmunity in a subset of these patients." (PMID 40566617, 2025). "Therefore, further investigation is warranted to identify if an emergence of anti-SP1 in SS or other autoimmune conditions signifies failed central tolerance involving AIRE." (PMID 34249010, 2021).
biliary atresia (2 papers, 2010 to 2025). A rare, biliary tract disease characterized by progressive obliterative cholangiopathy of the intra- and extrahepatic bile ducts, occurring in the embryonic/ perinatal period, leading to severe and persistent neonatal jaundice and acholic stool. "We wish to study the existence or absence of robustness for such genetic interaction networks centered on the gene SP1 and involved in three familial diseases: familial angioedema, osteogenesis imperfecta, and biliary atresia." (PMID 41465403, 2025). "E2F regulates cellular proliferation and TGFβ1-induced expression of matrix substrates, while SP1 is a potent inducer of extracellular matrix expression by fibroblasts, but neither has been linked to pathogenesis of biliary atresia." (PMID 20465800, 2010).
breast invasive carcinoma (2 papers, 2019). "In addition, the TCGA dataset analysis was carried out to analyze the impact of high expression of Sp1 and TMBIM6 on the prognosis of breast invasive carcinoma patients." (PMID 31336725, 2019).
cholestasis (2 papers, 2016 to 2025). Impairment of the bile flow caused by obstruction within the liver, or outside the liver in the bile duct system. "Recently, we have shown that transcription factor (TF) SP1 negatively regulates NOS-3 expression during GCDCA-induced cholestasis through direct binding to the NOS-3 promoter (pNOS-3) in an oxidative stress dependent manner." (PMID 27490694, 2016). "Online data mining suggested that cholestasis might upregulate ACER3 via transcription factors SP1, EGR1, and STAT3, which were determined as potential regulators of ACER3 expression and known to be activated by cholestasis." (PMID 40025008, 2025). "However, since these two compounds have also been described as SP1 inhibitors with antioxidant properties, and both, SP1 and oxidative stress, are related to NOS-3 expression regulation during cholestasis, these results could not be directly attributed to the inhibition of AP-1." (PMID 27490694, 2016).
cryptococcal infections (2 papers, 2022 to 2023). "Studying the mechanism by which SP1 damages the polysaccharide capsule and investigating the potential benefits of SP1 in removing C. neoformans from the host provides baseline data to develop a therapeutic strategy against refractory cryptococcal infections." (PMID 36916981, 2023). "Our data imply that SP1 has the potential to be developed into a treatment option for cryptococcosis." (PMID 35019693, 2022). "This study laid a foundation for the potential of SP1 to treat cryptococcosis." (PMID 36916981, 2023). "The effect of SP1 on the capsule could be an advantage for the treatment of cryptococcosis." (PMID 35019693, 2022).
cutaneous squamous cell carcinoma (2 papers, 2023 to 2025). "Prior studies have demonstrated that GBP1 interaction with SP1 promotes STAT3 activation, which enhances proliferation and invasion in cutaneous squamous cell carcinoma." (PMID 40975978, 2025). "The pro-oncogenic LncRNA HOTAIR interacts with and upregulates Sp1, which induces DNMI1, and transcriptional repression of miR-199a-5p and targeting downregulation of Sp1 or DNMI1 was found to decrease stemness and progression of cutaneous squamous cell carcinoma." (PMID 36982239, 2023).
Depression (2 papers, 2021). "For the first time, we found that miR-15b-5p/miR-92b-3p mimics could inhibit MAOA activity through directly targeting PTGS1 via NF-κB1/SP1 signaling and may be developed as new drug targets for depression treatment in OSA patients." (PMID 34829725, 2021). "Thus, miR-92b-3p might play anti-inflammatory, antioxidant, and MAOA-inhibiting roles in the progression of OSA and the development of depression by regulating PTGS1 via NF-κB1/SP1 signaling." (PMID 34829725, 2021).
diabetic cardiomyopathy (2 papers, 2024). Diabetic cardiomyopathy is a disorder of the heart muscle in people with diabetes. "Studies have implicated SP1 in the progression of diabetic cardiomyopathy." (PMID 39062521, 2024). "The protective effect of exercise on diabetic cardiomyopathy may be attributed to the reduction of Sp1 O-GlcNAcylation levels." (PMID 39252788, 2024). "Therefore, SP1 plays a significant role in the progression of diabetic cardiomyopathy by controlling cardiomyocyte apoptosis." (PMID 39062521, 2024). "This reduces phosphorylation levels of Sp1 at Ser/Thr, further increasing TGFβ1 and PAI-1 transcription, leading to decreased cardiac systolic function and accelerating diabetic cardiomyopathy progression." (PMID 39252788, 2024).
dysplasia (2 papers, 2013 to 2014). A usually neoplastic transformation of the cell, associated with altered architectural tissue patterns. "In intestinal metaplasia, the frequency of high SP1 expression increased to 31.6%, and the proportion of cases exhibiting high SP1 expression increased further to 50.0% and 56.3% in low- and high-grade dysplasia, respectively." (PMID 23437057, 2013).
E. coli infection (2 papers, 2018 to 2021). "SP1 expression in marrow lin+, lin−c-kit+, and LKS cells was significantly increased 18 h following E. coli infection." (PMID 29535725, 2018).
gall bladder carcinoma (2 papers, 2015 to 2023). "In addition, As2O3 down-regulates cyclin D1 transcription via a reduction of Sp1 transcription factor in gallbladder carcinoma cells." (PMID 26359868, 2015).
hemorrhagic stroke (2 papers, 2021 to 2023). A stroke caused by a bleed on the brain. "Pharmacological selenium inhibits GPX4-dependent ferroptotic death, and selenome protects neurons and improves behavior following hemorrhagic stroke through regulating TFAP2c and Sp1." (PMID 35264947, 2021).
hyperhomocysteinemia (2 papers, 2017 to 2024). A serious metabolic condition caused by mutations in the MTHFR gene, medications, or nutritional deficiency. "In vivo studies using CBS+/−, a model for hyperhomocysteinemia, and sibling CBS+/+ control mice revealed that deficiency of CBS upregulates cardiac CSE, plausibly by inducing SP1." (PMID 28623294, 2017).
Hyperinsulinemia (2 papers, 2017 to 2025). An increased concentration of insulin in the blood. "We noticed that another member of the SP family, SP3, is also predicted by GLADIATOR to participate in the hyperinsulinism module, and found that a recent study suggests a new mechanism involving both SP1 and SP3 in mediating insulin activation of glucokinase transcription." (PMID 28549478, 2017). "In vivo hyperinsulinemia and in vitro exposure of cardiomyocytes to high glucose or insulin led to an increase in SGLT1 expression by increasing binding of the transcription factors HNF-1 and Sp1 to the SGLT1 gene (Slc5a1), and the transcript stabilizer HuR to SGLT1 mRNA." (PMID 40932483, 2025).
hypertrophic cardiomyopathy (2 papers, 2024). A condition in which the myocardium is hypertrophied without an obvious cause. "Research has shown that Sp1 deficiency induces hypertrophic cardiomyopathy (HCM), while Sp1 overexpression holds therapeutic potential for HCM by ameliorating pathological characteristics in HCM mouse models, such as cardiomyocyte hypertrophy and muscle fiber disorders." (PMID 39252788, 2024).
infertile (2 papers, 2012 to 2021). "We found KIF2C-miRNAs (has-miR-3154, 6075, 6760-5p, 1251-5p, 186-sp)-TFs (EP300, SP1) might work in spermatozoa of infertile men." (PMID 34591790, 2021).
intervertebral disc degeneration (2 papers, 2025).
keratoconus (2 papers, 2013 to 2025). A degenerative, structural disorder of the eye, characterized by a cone-shaped protrusion of the cornea. "Sp1 is believed to play a role in keratoconus disease progression by supporting the increased expression of degradative enzymes such as cathepsin-B and suppression of proteinase inhibitors such as α1-proteinase inhibitor (α1-PI)." (PMID 23533700, 2013). "Expression of Sp1 is upregulated in a severe cornea-thinning disease called keratoconus." (PMID 23533700, 2013). "Downregulation of α1-PI in the corneal epithelium mediated by Sp1 may be a key event in keratoconus progression, supporting the possibility that the corneal epithelium also is involved in keratoconus, along with the stroma." (PMID 23533700, 2013).
kidney cancer (2 papers, 2014 to 2019). Primary or metastatic malignant neoplasm involving the kidney. "SP1 was upregulated in kidney cancer samples and indicated good prognosis when highly expressed, which revealed that SP1 tended to be a protective factor with higher gene expression." (PMID 31727869, 2019).
liver cirrhosis (2 papers, 2023 to 2025). "Obviously, the expressions of PPP1R12A, SP1 and SMARCAD1 in HCC tissues were higher than those in the liver cirrhosis tissues, which were opposite to the expression trend of KLF2 in HCC." (PMID 37386390, 2023). "1.SP1, RELA, and NFKB1 were identified as key regulators in regulating the liver cirrhosis process." (PMID 41586310, 2025).
lupus (2 papers, 2014 to 2023). "CREMα is implicated in immune disorders such as Systemic Lupus Erythematosus (SLE), where its expression is enhanced by transcription factor SP1 and histone lysine methyltransferase SET1 binding to the Crem P1 promoter." (PMID 37628737, 2023).
malignant glioma (2 papers, 2003 to 2021). A grade III or grade IV glioma arising from the central nervous system. "Upregulation of LINC01614, induced by SP1, promotes malignant glioma progression by modulating the miR-383/ADAM12 axis." (PMID 35047016, 2021). "In the present study, our findings with serial deletion or mutation assays of the p181 promoter indicated that c-Myc sites within p181 were less important for transcriptional regulation of the hTERT gene in malignant glioma cells than Sp1 sites." (PMID 12942127, 2003). "In case of malignant glioma cells, inhibition of Sp1 sites-dependent transcription reduced cell growth as well as invasiveness." (PMID 12942127, 2003).
meningitis (2 papers, 2015 to 2016). A disorder characterized by acute inflammation of the meninges of the brain and/or spinal cord. "In this context, we selected 16 genes coding for S. pneumoniae virulence proteins and compared their carriage within two large collections of invasive isolates from France and the African meningitis belt, with a particular focus on Sp1 and meningitis isolates." (PMID 26214695, 2015). "Most virulence genes were carried by the European ST306 clone but were lacking on Sp1 isolates circulating in the African meningitis belt, where a more serious pattern of infection is observed." (PMID 26214695, 2015). "We demonstrated that while most of studied genes were harboured by the invasive Sp1 ST306 clone, they were absent in both Sp 1 CCs circulating in the African meningitis belt." (PMID 26214695, 2015).
metastatic cancer (2 papers, 2018 to 2025). A carcinoma which has spread from the original site of growth to another anatomic site. "To further validate SP1's regulation of WNT pathway genes, we performed SP1 knockdown in two metastatic cancer cells MDA-MB-231 and HCT116." (PMID 39748426, 2025). "Targeting SP1 TFs has been previously shown to disrupt metastatic cancer in vitro." (PMID 39748426, 2025). "Therefore, these Sp1 inhibitors may have a therapeutic potential for the treatment of ZEB2-dependent metastatic cancers." (PMID 29416649, 2018). "ChIP-seq analysis further showed that SP1 binds at the regulatory elements of these genes only in metastatic cancer cells and not in non-metastatic cells." (PMID 39748426, 2025). "The results show a clear occupancy of SP1 at the regulatory elements of these genes in independent metastatic cancer cells (MDA-MB-231) but not in non-metastatic (HCC1806) cancer cells." (PMID 39748426, 2025).
metastatic disease (2 papers, 2024 to 2025). "Here, degree centrality scoring in the high metastatic cluster gene regulatory network configuration successfully recognised key TFs associated with metastatic disease, such as SP1 and E2F4." (PMID 39748426, 2025). "Furthermore, RNA-seq analysis in a large cohort revealed that the expression of SP1-target WNT pathway genes were significantly elevated in metastatic tumors compared to the controls." (PMID 39748426, 2025). "Accordingly, increased expression of SP1 and peri-nuclear staining of XPO1 only showed in both prostatic Solid-PCa and lung metastatic tumor cells but not in Adeno-PCa cells of TripleTg mice and PCa samples of DoubleTg mice in adjacent tissue sections." (PMID 38336745, 2024).
Miscarriage (2 papers, 2021 to 2024). A pregnancy that ends at a stage in which the fetus is incapable of surviving on its own, defined as the spontaneous loss of a fetus before the 22th week of pregnancy. "Of interest, SP1, a TF associated with recurrent miscarriage, was found to be among the top TF-associated motif hits (p = 1e-16, q-value<0.0001) in regions gaining H3K4me3 in sperm from obese sires." (PMID 39612469, 2024). "An increased miRNA-4497 level in the placental villus tissues associated with recurrent miscarriage may down-regulate SP1 expression." (PMID 33579314, 2021). "Further examination of miRNA-4497 and SP1 expression levels in miscarriage cases may help to verify how specific the observed changes are for RM." (PMID 33579314, 2021).
multiple sclerosis (2 papers, 2021). A progressive autoimmune disorder affecting the central nervous system resulting in demyelination. "In the panels shared by PD and MSA was a transcription factor playing, SP1, which is an important regulator of neuroinflammation in multiple sclerosis." (PMID 33584195, 2021).
myopia (2 papers, 2021 to 2024). "Furthermore, the expression of Sp1 and collagen I in the scleral tissues decrease with the time of form deprivation myopia at the mRNA and protein levels, suggesting that Sp1 may be involved in the regulation of type I collagen synthesis/degradation during myopic remodeling of the sclera." (PMID 33996791, 2021).